CD4 (CD4 molecule)
Diseases named in the same sentence as CD4 in open-access papers (continued):
Sharing a sentence is not in itself a finding about the gene and the disease.
thyroiditis (57 papers, 2004 to 2026). Inflammation of the thyroid gland. "Subjects with a higher CD4+/CD8+ ratio also had a higher risk of having a thyroid volume >2 SDS and a higher ATD dose." (PMID 35654927, 2022). "Recent scRNA‐seq studies involving patients with NSCLC have observed an elevation in CD4+ Th2 cells and CD4+ Th17 cells linked to pneumonitis and thyroiditis, respectively, highlighting their proinflammatory effects and the potential occurrence of organ‐specific toxic effects." (PMID 38451000, 2024). "In the study of autoimmune thyroid disease (AITD), cytokines such as IFN-γ induce TFC to express MHC-II molecules, which present thyroid autoantigens to CD4+ T cells, thereby breaking the immune tolerance of the host." (PMID 40535343, 2025). "A scRNAseq analysis of peripheral circulating T cells from patients with tumors treated with ICIs revealed a significant increase in the abundance of CD4+ TH17 cells in those who developed ICI-induced thyroiditis compared to control patients." (PMID 40535343, 2025). "Murine models demonstrate CD4+ T-cell infiltration in thyroid tissue during irAEs, implicating Th1/Th17-driven inflammation in destructive thyroiditis." (PMID 40881122, 2025). "In a mouse model, administration of anti-PD1 antibodies combined with thyroid globulin induced thyroid-related immune ADEs, with CD4+ T cells expressing granzyme B directly damaging thyroid follicular cells." (PMID 40894206, 2025). "The most common thyroid disorder found in people with low CD4 counts or long-term cART exposure is subclinical hypothyroidism, which can develop into overt disease if not detected." (PMID 41301708, 2025). "Recently, it has been shown that CD4 + lymphocytes play an important role in the mechanism of ICI-induced destructive thyroiditis." (PMID 38962048, 2024). "The frequency of peripheral cytotoxic CD4+ T cells was shown to correlate with destructive thyroiditis induced by anti-PD-1 therapy." (PMID 36261600, 2022). "Thyroiditis is related to viral attack or antibody production to thyroid antigen via CD4 Th1 response, which results in progressive destruction of the thyroid gland." (PMID 34567510, 2021). "Both thyroiditis and autoantibody generation can be abolished by depleting the populations of CD4+ T-cells, CD8+ T-cells or B-cells, indicating a critical role of lymphocytic infiltration in the development of iodine-induced AIT." (PMID 25050783, 2014). "Interestingly, CD4+ T cells also play a crucial role in PD-1 inhibitors induced destructive thyroiditis." (PMID 40388765, 2025). "Furthermore, in individuals with ICI-thyroiditis, IL-21+ CD4+ Tfh cells are key drivers of thyroid autoimmune attack." (PMID 40626363, 2025). "The adenosine receptors on the dendritic cells (DCs) can interact with CD26 on the surface of T cells to mediate the CD4+ T cell differentiation, DCs deliver antigens to CD4+ T cells so as to stimulate the production of thyroid related antibodies, thereby destroying the thyroid follicular cells." (PMID 38774877, 2024). "For endocrine‐related irAEs, thyroiditis is often driven by anti‐PD‐1‐activated CD4+ T cells." (PMID 38451000, 2024). "Thyroiditis results in elevation of the mTOR/HIF-1α/HK2/glycolysis pathway in CD4+ T cells." (PMID 34149615, 2021). "Alterations in immune cell populations during pregnancy have been linked to maternal disease, including low postpartum T cell levels in mothers who develop postpartum psychosis and high CD4/CD8 T cell ratios with higher levels of activated T cells in women who develop postpartum thyroiditis." (PMID 32582882, 2020). "Importantly, mice that received IL-1β-exposed CD4+CD25+ T cells developed less severe thyroiditis as compared to control CD4+CD25+ T cell recipients." (PMID 21779356, 2011).
thyroiditis (continued). "And enriched in the autoimmune thyroid disease pathway, both autoantibodies and thyroid-specific cytotoxic T lymphocytes (CTLs) have been proposed to be responsible for autoimmune thyrocyte depletion, and self-reactive CD4+ T lymphocytes (Th) recruit B cells and CD8+ T cells (CTL) into the thyroid." (PMID 35155440, 2021). "We found that thyrotoxic IFN-γ+CD8+ T cells in the thyroid were driven by IL-21 from CD4+ Tfh cells and inhibition of IL-21 prevented ICI-thyroiditis." (PMID 40626363, 2025). "CD4+/CD25+/Foxp3+ regulatory T-cells and Foxp3 gene expression were reduced in mice with iodine-induced thyroiditis, and the number of regulatory T-cells was negatively related to the severity of thyroiditis." (PMID 25050783, 2014). "The result indicates that CD4+ T cells may assist CD8+ T cell activation, highlighting immune collaboration in ICI-induced thyroiditis." (PMID 40535343, 2025). "The median CD4 level of PLWHD with thyroid disorders was, however, significantly lower than those PLWHD without thyroid disorders: CD4 = 376.08 ± 333.30 vs. 509 ± 341.75, respectively; p = 0.004." (PMID 33240534, 2020). "This view is supported by the finding that thyroid cells during thyroiditis may express the major histocompatibility complex (MHC) class II proteins, a critical structure for antigen presentation to CD4+ T lymphocytes." (PMID 15292926, 2004). "While a role for IL-21 in ICI-T1DM has not been described, we showed in mice and humans with ICI-thyroiditis that IL-21 from CD4+ cells could augment effector molecules (IFN-γ, granzyme B) and chemokine receptors on thyrotoxic CD8+ T cells." (PMID 40626363, 2025). "However, in the absence of concomitant immune-mediated thyroid pathology, the role of CD4+ and CD19+ cells is much less significant." (PMID 39936166, 2025). "Univariate and multivariate logistic regressions were used to predict effect of thyroid and reproductive dysfunctions on HIV infected women irrespective of the phases of menstrual cycle after adjusting for possible confounding variables age, BMI, viral load, CD4 count and HAART." (PMID 28723963, 2017). "Clinically, patients with ICI-induced thyroiditis were found to have significantly elevated levels of CD27+ CD4+ TEM cells in their PBMCs, compared to those without thyroid involvement." (PMID 40535343, 2025). "Meanwhile, another study has found that patients with pembrolizumab-induced thyroiditis had elevated circulating CD56+CD16+ natural killer cells, without elevation of the CD3+ T-cell count, or the CD4+ and CD8+ T-cell sub-populations." (PMID 35681667, 2022). "PLWH who receive cART treatment or have low CD4 counts may benefit from TSH and FT4 tests performed on a regular basis to detect thyroid problems early, though no current guidelines recommend routine monitoring for stable asymptomatic patients." (PMID 41301708, 2025).
acute GVHD (56 papers, 2008 to 2025). "Conventional CD4+ T-cell recovery, their activation status, and metabolic signature were associated with acute GVHD and in particular the CXCL9-CXCR3 axis." (PMID 39482353, 2025). "Hypomagnesemia was associated with delayed CD4+ T cell recovery, prolonged engraftment, and an increased risk of acute GVHD." (PMID 40806047, 2025). "The phosphorylation of ERK1/2 in CD4+ T cells at day +30 is associated with acute GVHD patients, and its reduction corresponds to the alleviation of acute GVHD symptoms." (PMID 39840040, 2024). "Our model also predicted that a raised initial CD4 concentration was associated with incidence of acute GvHD." (PMID 28074473, 2017). "In a separate GVHD study, we have found that CD4+CD25− Tcon cells are very potent in inducing lethal acute GVHD in that 2–5×104 B6 Tcon cells would cause substantial lethality to BALB/c hosts within 10 days after allo-HCT." (PMID 27774524, 2016). "In the current study, the increased populations of CD8+ Treg cells along with CD4+ Treg cells by curcumin treatment were associated with attenuated acute GVHD severity in a murine model." (PMID 23840617, 2013). "Furthermore, in hematopoietic stem cell transplantation, high Treg cell:CD4 T cell ratios are associated with reduced acute graft-versus-host disease and reduced overall mortality." (PMID 35591976, 2022). "Furthermore, PLX2853 significantly reduced IL-23R+ and pathogenic CD4+ IFNγ+ IL-17+ double positive T cell infiltration in gastrointestinal tissues in an acute GVHD murine model." (PMID 34722316, 2021). "Conventional CD4 + T cells (Subset V) were statistically significantly increased in patients with grade II to IV acute GVHD compared to those with acute GVHD grade 0–I and mild to moderate chronic GVHD compared to those without chronic GVHD." (PMID 40141165, 2025). "Graft T-cell content correlated with CD4+ T-cell reconstitution and acute graft-versus-host disease." (PMID 38200046, 2024). "In B6→F1 acute GVHD, B6 donor CD4 T cells produce a strong initial IL-2 response, which in turn promotes a Th1-dominant response consisting of robust TNF and IFNγ production." (PMID 38915570, 2024). "On the other hand, GzmB-mediated activation-induced death of CD4+ T cells inhibits murine acute GVHD, while GzmB contributes to the optimal graft-versus-tumor effect mediated by CD4+ T cells." (PMID 38846935, 2024). "Pathological analysis of patients with skin acute GVHD revealed high expression of CCR5 in CD4+ and CD8+ T cells." (PMID 39840040, 2024). "used APC (II+/+) expressing MHC II-deficient (II-/-) mice to examine the capacity of DCs and B cells to initiate acute GVHD (resistant to CD4-dependent GVHD)." (PMID 38124750, 2023). "Previous studies in allo-HSCT animal models showed that the addition of highly purified CD4+CD25+FoxP3+Treg cells resulted in a reduction of acute GVHD." (PMID 38124750, 2023). "This is in contrast to CD4+ T-cell-mediated murine acute graft-versus-host disease, which can be prevented by tofacitinib." (PMID 36882462, 2023). "Similar to these results, our data also showed that the blockade of BAFF signaling acts as a reciprocal regulator of the Th1 and Th2 populations in CD4+ T cells in the acute GVHD model." (PMID 36561743, 2022). "MiR-150, which also showed downregulated expression in patients with ASO, has been reported to negatively regulate the function of CD4+ T cells through the AKT3/Bim signaling pathway in acute graft-versus-host disease." (PMID 35428200, 2022). "Our group has reported that the blockade of BAFF through belimumab therapy or blocking of IL-21 signaling plays critical roles in the generation of CD4+CD25+Foxp3+ Treg cells in acute GVHD after allo-BMT." (PMID 36561743, 2022). "CD4+ alloreactive T cells are required for initiation and propagation of acute GVHD, both in mouse models and in clinical studies." (PMID 34291733, 2021).
acute GVHD (continued). "Another clinical trial uses pan-HDACi panobinostat, combined with glucocorticoids, as primary treatment for acute GVHD demonstrates an enhanced H3 acetylation in both CD4+ and CD8+ T cells." (PMID 34305954, 2021). "Acute GVHD is induced by numerous graft-derived immunocytes, including the naive CD4+T cells from donors, which can differentiate and exert cytotoxicity on multiple organ systems of the allo-HSCT recipients." (PMID 34036106, 2021). "Chronic and acute GVHD are characterized by activation and proliferation of conventional CD4+ T cells." (PMID 32612177, 2020). "In summary, our data showed that obese donor aggravated acute GVHD severity through regulating CD4+ T cell induced-type I inflammation and differentiation of Tregs." (PMID 29088831, 2017). "In our model, donor-derived CD8+ T-cells, CD4+ T-cells, and macrophages within Th1 cytokine milieu induced acute GVHD of the kidney that have classically been considered the main immune mechanism mediating GVHD pathogenesis." (PMID 25541735, 2014). "In patients with acute GVHD after HLA-sib or MUD HSCT, Tregs frequencies measured at disease onset as the percentage of CD4+CD25brightFoxp3+ T cells over total nucleated cells were reported to inversely correlate with acute GVHD grading." (PMID 23531639, 2013). "Interleukin-17-producing cells increase among CD4+ lymphocytes before overt manifestation of acute graft-versus-host disease." (PMID 23843069, 2013). "Furthermore, a positive correlation was observed between conventional CD4 + T cells (subset V) and the severity of acute GVHD." (PMID 40141165, 2025). "Specifically, acute GVHD mice exhibit engraftment of both CD4 and CD8 donor T cells with profound depletion of F1 B cells, whereas chronic GVHD mice exhibit significant engraftment of only the donor CD4 T cell subset coupled with significant expansion of F1 B cells and autoantibody production." (PMID 38915570, 2024). "Finally, patients with acute GVHD exhibited a higher CD4/CD8 ratio and higher NK cell recovery within the first year posttransplantation." (PMID 39737173, 2024). "This study suggests that BAFF blockade might modulate CD4 +T-cell-induced acute GVHD early after allo-HSCT and the possibility of simultaneously controlling chronic GVHD, which may appear later after allo-HSCT." (PMID 36561743, 2022). "In conclusion, the results of the present study show that a BAFF blockade might modulate CD4+ T-cell-induced acute GVHD early after allo-BMT and the possibility of simultaneously controlling chronic GVHD, which may appear later after allo-BMT." (PMID 36561743, 2022). "Furthermore, STAT3-phospho-(Tyr705) is increased in circulating CD4+ T cells from allotransplant recipients prior to the onset of acute GVHD and seems to induce differentiation of pro-inflammatory Th17 cells and inhibition of Treg development." (PMID 35566660, 2022). "Since several experimental approaches indicate that CD4 T cells play an important role in initiation and progression of acute GVHD, the contribution of the different CD4 T helper (Th) cell subtypes in the pathomechanism and regulation of the disease is a central point of current research." (PMID 35069590, 2021). "Since several experimental approaches indicate that CD4 T cells play a key role in initiation and progression of acute GVHD, the contribution of the different CD4 T helper (Th) cell subtypes in the pathomechanism and regulation of the disease is a central point of current research." (PMID 35069590, 2021). "However, in the recipients transplanted with sorted CD8+ T cells and that developed little acute GVHD, de novo-generated donor-type CD4+ T cells are required for induction of chronic GVHD." (PMID 34539630, 2021). "In accordance with previous reports, TCD and subsequent CD4+ MC were associated with a low incidence of GVHD: none of our patients experienced ≥grade 2 acute GVHD or extensive chronic GVHD." (PMID 34950586, 2021).
acute GVHD (continued). "In the univariate analysis, DSAs (MFI ≥ 1000, P = 0.076), grade II–IV acute GVHD (P = 0.033), infused CD4+ (P = 0.024) and CD3+ cells (P = 0.088), donor-recipient relationship (P = 0.097), and disease status at the transplantation (P = 0.029) were associated with TRM." (PMID 28484721, 2017). "Strong pre-clinical work supports the use of CD4+CD25+ Tregs to suppress acute GVHD." (PMID 24575095, 2014). "However, eight patients developed acute GVHD, displaying lower proportions of IL-17-producing CD4 cells on the day of acute GVHD compared to initial measurements." (PMID 23843069, 2013). "In contrast, CD4+Foxp3+ splenocytes were increased in the curcumin-treated acute GVHD animals." (PMID 23840617, 2013). "Both the percentage (39.7%, range 20.7–60.7 vs. 32.5%, range 3.25–49.44, P = 0.025 ) and absolute levels (87.5×106/L, range 19–218 vs. 55.3×106/L, range 4–182, P = 0.009) of CD161+CD4+ T cells in peripheral blood were found to be significantly reduced in patients with acute GVHD." (PMID 23226545, 2012). "Indeed, a recent study using genetic ablation of the MHCII molecule in Ccl19-Cre+ cells revealed that FRCs shape CD4+ T cells’ responses in a murine model of acute graft-versus-host disease (GVHD) with reduced expansion of FoxP3-expressing CD4+ T cells and invariant natural killer (NK) T cells." (PMID 38038708, 2024). "In the multivariate analysis, only the lower frequency of CD4- iNKT cells could predict higher incidence of acute GVHD in patients receiving BM and PBSC grafts and higher CD4- iNKT cell ex vivo expansion capacity was associated with lower rates of grade 2–4 GVHD in patients receiving PBSC grafts." (PMID 33680931, 2020). "In pediatric patients with skin acute GVHD, the proportion of CCR10+ CD4+ subgroups in peripheral blood T cells is significantly higher than in non-GVHD patients, and this subgroup vanishes after the resolution of acute GVHD." (PMID 39840040, 2024). "Overall, transfer of either CD4+ or CD8+ Glut1T-KO T cells significantly improved long-term survival and ameliorated acute GVHD." (PMID 35296079, 2022). "STAT3 (Tyr705) responses were stronger for patients with previous acute GVHD; CD3+CD4+ cells from GVHD patients showed an additional STAT3 (Ser727) response, whereas patients without acute GVHD showed additional mTOR (Ser2448) responses." (PMID 35566660, 2022). "Patients receiving this ligand on the day of transplantation exhibited improved reconstitution of Helios+ Treg cells (defined as higher than 12% of CD4+ cells at any timepoint after allo-HCT) and lower incidence of grade 2–4 acute GVHD." (PMID 33680931, 2020). "In acute graft-versus-host disease (GVHD), naive donor CD4 cells recognize alloantigens on antigen presenting cells in target organs, including skin, intestine and lung." (PMID 29203869, 2017). "The CD62L+ cell subset is a more potent suppressor than the CD62L− population or unfractionated CD4+CD25+ Treg cells; therefore, only the CD62L+ subpopulation of CD4+CD25+ regulatory T cells protects from lethal acute GVHD." (PMID 25948100, 2015). "Another example is the CD62L+ subpopulation of CD4+CD25+ Tregs, which appears to most effectively treat acute GVHD." (PMID 24575095, 2014). "In the present study, renal inflammation in acute GVHD was accompanied by infiltration of CD8+ T-cells and CD4+ T-cells." (PMID 25541735, 2014). "In the mouse, IL-18 has a protective effect on CD4(+)-mediated acute GVHD, and blockade of IL-18 accelerates acute GVHD-related mortality in mice." (PMID 18818761, 2008). "We extended these studies on the potential induction of Foxp3 expression in CD4+ non-Treg by examining a cohort of patients who were developing acute GVHD or who manifested signs of chronic GVHD following HCT for malignancies." (PMID 37350974, 2023). "We then performed a correlation analysis between these CD4+ subset proportions and the severity of acute graft-versus-host disease (aGVHD) in LE and non-LE patients." (PMID 37626859, 2023).